PTX3 (pentraxin 3)
Diseases named in the same sentence as PTX3 in open-access papers (continued):
Sharing a sentence is not in itself a finding about the gene and the disease.
lung carcinoma (continued). "With cancer, previous studies on lung cancer have confirmed that patients produce PTX3 and that there are differential expressions of PTX3 amongst the subtypes of lung cancer with significantly higher levels in small cell lung cancer (SCLC) than non-small cell lung cancer (NSCLC)." (PMID 38730589, 2024). "Additionally, in cell line experiments of bladder, breast, prostate, lung cancers, melanoma, and sarcomas, PTX3 functioned as an antitumoral factor." (PMID 39594709, 2024). "Obtained results clearly demonstrate the importance of mentioned regulators for LUAD/LUSC progression: it was shown that up-regulation of PTX3, TIMP1, SERPINE1, and PLAUR not only on mRNA, but also on protein level was significantly associated with poor survival in patients with lung cancers." (PMID 34807957, 2021). "Different studies analyzed the role of PTX3 as biomarker in lung cancer." (PMID 31019517, 2019). "Similarly, high PTX3 levels were correlated with worse progression-free survival in patients with lung cancer and chronic obstructive pulmonary disease, and with overall survival and disease-free survival in small-cell lung carcinoma (SCLC)." (PMID 31019517, 2019). "The present study suggests that the novel inflammatory marker PTX-3 may be used in the diagnosis and follow-up of prognosis as a biomarker of inflammatory response in patients with lung cancer." (PMID 31086534, 2019). "It should be born in mind that PTX-3 levels are statistically significantly increased in patients with lung cancer and/or aged over 65 years, and the correlation between the PTX-3, CRP, and WBC levels in patients who underwent posterolateral thoracotomy was insignificant." (PMID 31086534, 2019). "A recent study on 1358 individuals at high risk for lung cancer demonstrated that PTX3 levels were not predictive of pathology occurrence." (PMID 31019517, 2019). "Moreover, their study demonstrated no statistical correlation between PTX-3 levels and age, gender, peripheral blood leukocyte, or neutrophil counts, concluding that PTX-3 expression in bronchoalveolar fluid could be a diagnosis biomarker for lung cancer." (PMID 36499628, 2022). "However, several studies confirm that PTX-3 levels increased in more than 12 types of cancer, suggesting a non-specificity for this protein as a diagnostic marker in lung cancer." (PMID 36499628, 2022). "We suggest that the novel marker PTX-3 might be an indicator of the inflammatory response in patients to posterolateral thoracotomy with lung cancer and/or aged over 65 years, and might be used in the diagnosis and follow-up of the prognosis of patients with lung cancer." (PMID 31086534, 2019). "Initially, PTX3 was suggested to be useful only as a marker of lung carcinoma based on studies performed on lung cancer cell lines but more recent studies have determined that PTX3 could be used as a serum biomarker for the diagnosis and prognosis of lung carcinoma." (PMID 23755050, 2013). "In lung cancer cells, ginsenoside Rg3 inhibits ROS production, leading to NF-κB and HIF-1α-mediated downregulation of PTX3, and inhibits gemcitabine induced MDR of lung cancer cells." (PMID 40490812, 2025). "The level of PTX3 in bronchoalveolar lavage fluid is upregulated in lung cancer patients, especially in SCLC patients or lung cancer patients with obstructive pneumonia." (PMID 41479916, 2025). "Finally, considering the identified association of ALI-specific key genes with poor prognosis in LUAD/LUSC patients, TIMP1, SERPINE1, PLAUR, and PTX3 may be used as marker genes to control the severity of lung cancer progression in the case of accompanying pulmonary inflammation." (PMID 34807957, 2021). "In lung cancer tissues, HGF and PTX3 expression was downregulated and S100P expression was upregulated." (PMID 34745947, 2021).
lung carcinoma (continued). "Upon comparison of scale lung cancer, gland lung cancer, and SCLC, PTX-3 levels in the BALF of patients suffering from small cell lung cancer were drastically increased (cutoff value: 1933.0837 pg/mL; sensitivity for diagnosis: 81.00%; specificity: 61.10%)." (PMID 32587638, 2020). "Overlapping these gene sets revealed that 4 genes (PTX3, TIMP1, SERPINE1, and PLAUR) are common to both LUSC and LUAD patients, which may indicate the universality of these markers for the occurrence of lung malignant neoplasms." (PMID 34807957, 2021).
heart failure (37 papers, 2010 to 2025). Inability of the heart to pump blood at an adequate rate to meet tissue metabolic requirements. "Increased PTX3 not only predicts severe cardiac events but is also linked to worse long-term outcomes in patients with heart failure." (PMID 40470435, 2025). "In patients with heart failure, elevated plasma PTX3 levels associated independently with cardiac events but did not specifically correlate with coronary events." (PMID 24705587, 2014). "In CHF, PTX3 is related to more severe disease and worse outcomes, such as all-cause mortality, cardiovascular mortality, and hospitalization for decompensated heart failure." (PMID 24244639, 2013). "We previously reported that plasma PTX3 levels provide important prognostic information for risk stratification of patients with heart failure." (PMID 23372656, 2013). "PTX3 has also been implicated as a predictor of adverse clinical outcomes in patients with heart failure (n = 196) in a study with a median follow-up period of 655 days and an ejection fraction of less than 50%." (PMID 22347626, 2012). "Several studies have linked higher PTX3 levels with heart failure." (PMID 24705587, 2014). "On the contrary, previous studies had correlated higher plasma PTX-3 concentrations with heart failure." (PMID 38397422, 2024). "Novel biomarkers such as PENK, ST-2, GDF-15, Pentraxin-3, Galectin-3, and Osteopontin have recently emerged as potential prognostic indicators in heart failure patients." (PMID 36902318, 2023). "Pentraxin-3 (PTX3) and neprilysin have been associated with increased morbidity and mortality in chronic inflammatory disease and heart failure, but these biomarkers have been studied less in patients with ST segment elevation myocardial infarction (STEMI)." (PMID 35203485, 2022). "In patients with heart failure, PTX3 correlates with hospitalization rate, the occurrence of acute cardiovascular events, or cardiac death." (PMID 35563387, 2022). "In heart failure, the plasma PTX3 level provides important prognostic information for the risk stratification of patients." (PMID 34658887, 2021). "PTX3 level also predicts cardiac events in patients with heart failure (HF), suggesting a stratification of HF patients based on PTX3 plasma level." (PMID 27559355, 2016). "Elevated PTX3 levels have been reported in many types of cardiovascular disease, including acute coronary syndrome, congestive heart failure, and heart failure with normal ejection fraction." (PMID 23029266, 2012). "Additional studies introduced PTX3 as a prognostic biomarker in heart failure, both acute and chronic, which was unrelated to an AMI." (PMID 22577258, 2012). "In AMI patients, individual levels of PTX3 were attained independently of the extent of myocardial necrosis or incident heart failure assessed by the Killip class." (PMID 22577258, 2012). "In patients with heart failure, PTX3 has emerged as a predictor of adverse clinical outcomes." (PMID 40244022, 2025). "•Plasma IL-6 & PTX3 correlated to haemodynamics in patients with heart failure." (PMID 38560419, 2022). "Additionally, higher levels of PTX3 were associated with worse prognosis in patients with LHF-PH, which were also supported by the positive correlation of PTX3 and the heart failure biomarker NT-proBNP." (PMID 38560419, 2022). "On this point, an elevated level of circulating Pentraxin 3 (PTX3) – a member of a protein superfamily involved in the innate immune response – has been described as a marker of poor prognosis in patients with stable coronary artery disease or heart failure." (PMID 30733816, 2019). "The inflammatory response expressed by PTX3 had a significant relationship with age, heart failure, infarct size, impaired flow in the infarct-related artery, and renal function and positively correlated with neopterin, TNF-α, 8-hydroxy-2′-deoxyguanosine, and nitrite/nitrate." (PMID 25922551, 2015).
heart failure (continued). "Because CARE did not adjudicate heart failure endpoints, we did not examine the association between PTX3 levels and heart failure." (PMID 24705587, 2014). "Since increased plasma levels of PTX3 in patients with heart failure have been previously demonstrated, we examined whether PTX3 was produced by heart tissue after the TAC surgery." (PMID 23372656, 2013). "This is true even in patients with heart failure with normal ejection fraction (HFNEF), where PTX3 levels are elevated despite normal levels of other markers, like B-type natriuretic peptide (BNP)." (PMID 40244022, 2025). "PTX3 was assayed at randomization and after 3 months in 1,233 patients from the GISSI-Heart Failure trial (GISSI-HF) and 1,457 patients from the Controlled Rosuvastatin Multinational Trial in HF (CORONA)." (PMID 31057548, 2019). "Pentraxin 3 (PTX3) is rapidly produced in response to inflammatory signals, and high plasma PTX3 levels are seen in patients with heart failure." (PMID 23372656, 2013). "Heart failure, unstable angina/non-ST-elevation myocardial infarction (UAP/NSTEMI), and acute myocardial infarction (AMI), as well as higher PTX3 levels, are all linked to CKD and hemodialysis patients." (PMID 40470435, 2025). "PTX3 has demonstrated its role as a biomarker in both CAD and heart failure." (PMID 35563387, 2022). "Our study complements these previous observations by showing that the PTX3 plasma level of a cohort with mild symptomatic heart failure (NYHA classes I and II) and clinically stable heart failure is similar to that of healthy subjects matched for age and smoking history." (PMID 24244639, 2013). "Interestingly, PTX3 levels have been reported elevated in heart failure with normal ejection fraction and diastolic dysfunction." (PMID 28197227, 2015). "In addition, we investigated whether the combination of PTX-3 with the Heart Failure Survival Score (HFSS), the Seattle Heart Failure Model (SHFM), or the Meta-Analysis Global Group in Chronic Heart Failure (MAGGIC) improved the prognostic strength of these scales in the study population." (PMID 35566693, 2022).
coronary artery disease (35 papers, 2012 to 2025). "A separate study found that DNA methylation at the promoter region of PTX3 was associated with coronary artery disease only in men." (PMID 39976511, 2025). "Three meta-analyses consistently confirmed an association between plasma PTX-3 levels and worse outcomes in coronary artery disease (CAD) patients." (PMID 40340865, 2025). "Reduced methylation of the Ptx3 promoter is linked to increases in PTX3 plasma levels during coronary artery disease." (PMID 38529333, 2024). "Noteworthy, PTX3 expression has also been associated with the development of RA comorbidities such as vasculitis or coronary artery disease." (PMID 34248970, 2021). "Studies of adult coronary artery disease have identified PTX-3 as a predictor of all-cause mortality, cardiac death, and cardiac events." (PMID 32670996, 2020). "PTX3 has been associated with the incidence of coronary artery disease (CAD) and all-cause mortality in CAD patients." (PMID 32244987, 2020). "Unsurprisingly, lower blood cell Pentraxin 3 (PTX3) promoter DNA methylation levels were associated with higher PTX3 plasma levels and also neutrophil:lymphocyte ratio and presence of coronary artery disease." (PMID 32664454, 2020). "Prior work has shown that PTX3 is an inflammatory marker associated with coronary artery disease." (PMID 31998222, 2019). "A recent study showed a correlation between high levels of PTX3 and the severity of coronary artery disease." (PMID 36553147, 2022). "Several recent studies have also suggested that PTX3 is a useful biomarker for coronary artery disease and heart failure." (PMID 31998222, 2019). "A study on 594 patients with stable coronary artery disease (CAD) reported that PTX3 plasma levels were higher 24 h after PCI than before." (PMID 31057548, 2019). "Recently, PTX3 was suggested to be a prognostic marker also in patients with coronary artery diseases after drug stent implantation, and in patients with angina pectoris, in whom adverse cardiac events were related with PTX3 plasma levels." (PMID 27559355, 2016). "This is also observed in other patient groups, such as in patients with coronary heart disease, ischemic stroke and acute chest pain, where high levels of PTX3 predict poor outcome." (PMID 23658833, 2013). "Pentraxin-3, while less specific for coronary artery disease, may provide complementary insights in the context of AF, reflecting underlying atrial inflammation and disease chronicity." (PMID 40430046, 2025). "We hypothesized that galectin-3 and pentraxin-3 levels, along with inflammatory indices, would differ according to coronary artery disease severity and arrhythmia presence, reflecting their potential utility in risk stratification." (PMID 40430046, 2025). "Furthermore, PTX3 promoter methylation negatively correlates with plasma PTX3 levels in patients with coronary artery disease." (PMID 41479916, 2025). "Moreover, the meta-analysis of 15 studies, including 11,365 participants with coronary artery disease, showed that the adjusted odds ratios for composite poor outcomes increased by 32% per 1 ng/mL PTX-3 increment." (PMID 40340865, 2025). "In addition, in the presence of peripheral or coronary artery disease, PTX3 levels are significantly increased." (PMID 31057548, 2019). "Additionally, PTX3 expression is higher in patients who show IVIG resistance with coronary artery lesions than in those without coronary artery lesions, and is considered as a risk factor for coronary artery disease." (PMID 37941784, 2023). "Thus, research in adult human coronary artery disease in conjunction with our data implicates PTX-3 as a modulator of vascular dysfunction and remodeling and could have a specific role in KD-associated CAL." (PMID 32670996, 2020).
coronary artery disease (continued). "Nevertheless, the associations of PTX3, ficolin-2 and MASP-3 may uncover potential new causal mechanisms in the development and progression of coronary heart disease and risk for MI, lead to the generation of new hypotheses and suggest improvements to existing explanatory models." (PMID 28216633, 2017). "Our aim was to assess the prognostic value of PTX3 in patients with stable coronary artery disease (CAD) after drug eluting stent (DES) implantation." (PMID 25538378, 2014).
rheumatoid arthritis (35 papers, 2011 to 2025). A chronic, systemic autoimmune disorder characterized by inflammation in the synovial membranes and articular surfaces. "Accumulated evidence suggests that PTX3 is a potential marker associated with disease severity and mortality in diverse human pathological conditions, such as cardiovascular diseases, rheumatoid arthritis, chronic kidney disease, sepsis, and several types of cancers." (PMID 36530573, 2022). "Elevated expression of PTX3 has been implicated in many inflammatory and autoimmune diseases, including pulmonary infection, giant cell arteritis, atherosclerosis and rheumatoid arthritis." (PMID 25695775, 2015). "Increasing evidence shows that PTX3 is involved in the occurrence and development of multiple autoimmune diseases, such as rheumatoid arthritis and SLE." (PMID 40131879, 2025). "N-acetyltransferase 10 enhances PTX3 mRNA stability and translation efficiency via ac4C modification, upregulating PTX3 expression and promoting synovial aggression and inflammation in rheumatoid arthritis." (PMID 41479916, 2025). "In rheumatoid arthritis (RA), the biomarker pentraxin 3, along with its ligand C1q, has been reported to activate NLRP3." (PMID 38172822, 2024). "PTX3 is present in the occurrence and development of many auto-immunological diseases, such as rheumatoid arthritis, systemic sclerosis, systemic lupus erythematosus, and multiple sclerosis, as well as during microbial moieties." (PMID 37408184, 2023). "Pentraxin 3(PTX3), an important component of innate immunity, is elevated in the serum of RA patients and is considered as a new marker for the diagnosis of rheumatoid arthritis." (PMID 37426634, 2023). "Increased levels of PTX3 were also observed in different autoimmune disorders, such as small-vessel vasculitis and rheumatoid arthritis." (PMID 37025408, 2023). "PTX3 plays an important role in inflammation and in diseases such as rheumatoid arthritis, microbial infection, and atherosclerosis." (PMID 35739102, 2022). "PTX3 is primarily produced in the inflammatory sites, as was observed in the synovial tissue in rheumatoid arthritis." (PMID 29675428, 2018). "Enhanced expression of PTX3 was observed in synoviocytes and in synovial fluid from patients with rheumatoid arthritis (RA)." (PMID 23755050, 2013). "There has only been one report thus far showing that patients with rheumatoid arthritis (RA) have higher levels than controls of joint fluid PTX3." (PMID 23383162, 2013). "Moreover, in a previous work, we demonstrated that anti-PTX3 aAbs prevalence was low in rheumatoid arthritis patients, while detected in 50% of patients with SLE, a disease also associated with excessive NETosis." (PMID 26797217, 2016). "Since the definite role of PTX3 in rheumatoid arthritis is uncertain, the question of whether PTX3 suppresses or promotes RA inflammation is worthy of a future case-control association study." (PMID 23383162, 2013). "In addition, the synovial fluid from patients with rheumatoid arthritis contains strongly enhanced PTX3 levels, and synovial cells show a strong immunostaining for PTX3." (PMID 21915248, 2011). "In a study on rheumatoid arthritis (RA), pentaxin 3 (PTX3) was found to promote RA monocyte pyroptosis in a C1q-dependent manner." (PMID 35411030, 2022). "On the other hand, a decreased PTX3 production, as that observed in OP patients, could result in inadequate bone formation and an excessive PTX3 elevation in inflammatory conditions, such as in rheumatoid arthritis, could promote bone resorption, in both cases leading to bone mass loss." (PMID 29022895, 2017). "The expression of pentraxin 3 (PTX3), a molecule produced at sites of inflammation, was observed in the endothelial cells and adipocytes of the perivascular adipose tissue (PVAT) in a study of patients with rheumatoid arthritis and CAD." (PMID 40649128, 2025).
rheumatoid arthritis (continued). "Recently, our previous studies have demonstrated that PTX3 is a downstream target of CEBPD and contributes to inflammation-related disorders, such as atherosclerosis, Alzheimer's disease, rheumatoid arthritis, invasion and metastasis of cancer, and drug-resistant cancers." (PMID 36530573, 2022). "PTX3 expressed by numerous cell types after stimulation with cytokines (e.g. IL-1β and TNF-α), TLR agonists or microbes in inflammation is found to be increased in rheumatoid arthritis synovial fluid." (PMID 33746606, 2021). "Pentraxin 3 (PTX) promotes inflammation by activating the classical complement pathway and by facilitating antigen recognition by mononuclear phagocytes, and it has been shown to be elevated in the serum and synovial fluid of patients with rheumatoid arthritis." (PMID 34502384, 2021). "Moreover, synoviocytes from patients with rheumatoid arthritis constitutively express high levels of PTX3 mRNA and protein in vitro, and these were not affected by neutralization of TNF-α or IL-1β." (PMID 31787987, 2019). "For example, serum of rheumatoid arthritis (RA) patients could induce GSDMD-dependent pyroptosis in monocytes, which was promoted by PTX3 and C1q." (PMID 36057687, 2022).